RNU6-463P (RNA, U6 small nuclear 463, pseudogene)
Gene: Small nuclear RNA gene on chromosome 10 (105,534,659 to 105,534,765, forward strand). Ensembl gene ENSG00000207068.
Homologues: Orthologues: chimpanzee U6 (99% identical), rabbit U6 (93% identical), macaque U6 (89% identical), mouse Gm22828 (84% identical). Paralogues in human: RNU6-21P (93% identical), RNU6-1 (92% identical), RNU6-15P (92% identical), RNU6-2 (92% identical), RNU6-3P (92% identical), RNU6-4P (92% identical), RNU6-5P (92% identical), RNU6-6P (92% identical), RNU6-9 (92% identical), RNU6-12P (91% identical), RNU6-13P (91% identical), RNU6-17P (91% identical), and 1286 more.